CASP1 (caspase 1)
Diseases named in the same sentence as CASP1 in open-access papers (continued):
Sharing a sentence is not in itself a finding about the gene and the disease.
infection (continued). "Research so far has proven that caspase-1 is particularly important to overcome an infection with L. pneumophila." (PMID 27148204, 2016). "The subfamilies of inflammatory mediator (Casp1, Casp4) were up-regulated in response to infection with both B. pseudomallei WT and BM16." (PMID 27634329, 2016). "After B. melitensis 16M infection in differently treated cells, Western blot was used to detect the expression of Caspase-1 p10 protein levels at all of the time points." (PMID 27907115, 2016). "The increased susceptibility of Casp1/11-/-, Asc-/-, and IL-1r1-/- mice to Ft LVS infection in this study and IL-1β-/- mice in a previous study clearly underscore the critical requirement of IL-1β/IL-18 for protective immunity." (PMID 27926940, 2016). "NLRP3-dependent but caspase-1-independent necrosis has been reported to occur in response to infection with Mtb and Shigella flexneri." (PMID 27191591, 2016). "In an epithelial cell infection model with C. trachomatis, the translocated microbial effector Chlamydial protease-like activity factor (CPAF) inhibits ASC and caspase-1 at early time points during infection, which promoted host cell survival." (PMID 29056735, 2016). "Western blot analysis showed that active caspase-1 was observed at 6 h after HGPg infection, suggesting inflammasome activation in HGFs." (PMID 28083517, 2016). "More importantly, infection resulted in increased Pla2 activity in whole larvae, being this activation impaired by pharmacological inhibition of caspase-1 and, conversely, further increased by forced expression of Gbp4 and Caspa but not Asc." (PMID 27363812, 2016). "Caspase-1-dependent activation of caspase-7 in murine C57BL/6 macrophages upon infection with L. pneumophila requires detection of bacterial flagellin by the host proteins Naip5 and Nlrc4." (PMID 27148204, 2016). "It was reported that Sf-caspase-1 is typically cleaved first at D28 in baculovirus-infection-induced apoptosis, but it was typically cleaved first at D195 in UV-irradiation-induced apoptosis." (PMID 26977926, 2016). "The legS2 mutant showed higher replication than JR32 24, 48, and 72 h post-infection in casp-1-/-BMDMs." (PMID 26741365, 2016). "The expression of cleaved caspase-1 was significantly increased by wild-type D39 infection, whereas D39ΔPLY induced less increase of caspase-1 p10 expression." (PMID 26683708, 2015). "The immune contributions of pyroptosis and other cytokine-independent inflammasome effector mechanisms can make the role of Caspase-1 more prominent in certain infections." (PMID 26500655, 2015). "We found that C. burnetii pre-infection severely inhibited caspase-1 activation and pro-IL-1β processing in response to E. coli." (PMID 26687278, 2015). "BMDMs pre-infected with C. burnetii showed a reduction in caspase-1 activation in response to infection with both the WT Lp and flaA−L." (PMID 26687278, 2015). "Immunostaining of human macrophage-like cells following infection revealed limited formation of inflammasome foci with constituents of total caspase-1, ASC and NLRP3 in the presence of NleA." (PMID 26332984, 2015). "Ciaramella and co-workers also found that infection of human monocytes with MTB induced caspase-1-mediated apoptosis as well as TNFα and IL-1β production." (PMID 25887904, 2015). "Meanwhile, NLRP3-/- mice and Caspase-1-/- mice appeared to produce much less viruses at 72h of infection as compared to the WT controls." (PMID 26367131, 2015). "Using a variety of in vitro and ex vivo intoxication and infection models, we found that LukAB activates Caspase 1, promotes IL-1β secretion and induces necrosis in human monocytes." (PMID 26069969, 2015). "Like BMDMs, BMDCs derived from ASC-, AIM2-, or caspase-1-deficient mice are defective for cell death, IL-1β secretion and caspase-1 processing in response to infection with wildtype F. novicida." (PMID 25879288, 2015).
infection (continued). "MHV-3 infected PEMs and RAW264.7 cells exhibited with a significantly enhanced NLRP3, ASC, pro-Caspase-1 and its activated form (Caspase-1 p20) within 12h of MHV-3 infection." (PMID 26367131, 2015). "We found that pre-infection of BMDMs with C. burnetii for 24 h resulted in reduced caspase-1 activation and pro-IL-1β cleavage in response to a second infection with L. pneumophila." (PMID 26687278, 2015). "Caspase-1 activation is also important in resisting infection against Shigella, Legionella, Mycobacterium, and Listeria." (PMID 25879288, 2015). "Caspase-1-dependent response to Francisella is essential for host resistance in vivo as Casp1−/− mice succumbed faster to infection and carried higher bacterial burdens in the spleen and liver." (PMID 25879288, 2015). "On the contrary, the elevated expression of caspase-1 p10, IL-1β and IL-18 by D39 infection was further increased in response to treatment with 3-MA." (PMID 26683708, 2015). "We found that C. burnetii pre-infection inhibits caspase-1 activation and IL-1β processing in response to either WT Lp or flaA−L." (PMID 26687278, 2015). "Especially, D39 infection resulted in greater increases in the level of cleaved caspase-1, whereas it was decreased in D39ΔPLY-infected mice." (PMID 26683708, 2015). "Forty eight hours after infection, bacterial growth in the lungs of both Nlrc4−/− and Casp1−/−Casp11−/− mice had increased significantly compared to wild type mice (by 1.87 log10 CFU and 2.69 log10 CFU, respectively)." (PMID 25232720, 2014). "IL-1β plays a pivotal role in mediating host response to infection and danger molecules, and is released and secreted via inflammasome-dependent caspase-1 activation." (PMID 25000410, 2014). "The best elucidated effector mechanisms involved in the control of infections mediated by caspase-1 are the secretion of inflammatory cytokines IL-1β and IL-18 and the induction of pyroptosis." (PMID 25071770, 2014). "On day 10 post-infection, caspase-11 and caspase-1 activation were much higher in colon lysates of Rip2−/− mice compared to WT controls." (PMID 25254654, 2014). "Quantitative analyses of caspase-1 activity in mock- and HIV-infected microglia at 4 and 24 hr post-infection showed significant increases in caspase-1 activity in HIV-infected microglia at both time points." (PMID 24886384, 2014). "Here we found that P2X7R is necessary for caspase-1 activation during in vivo infection with P. chabaudi." (PMID 24453977, 2014). "By this process, abortive infection causes accumulation of incomplete HIV DNA transcripts, leading to interferon type 1 activation of caspase-1 resulting in cell death by pyroptosis, a highly inflammatory form of apoptosis." (PMID 25333710, 2014). "This caspase-1 independency was confirmed in a subsequent experiment performed to further investigate this process through infection of caspase-1 KO mice." (PMID 25162221, 2014). "The microarray analysis of splenocytes from C57BL/6 at 6 days post-infection demonstrates enhanced expression of various genes from the inflammasome pathway, including Casp1 and Il1b." (PMID 24453977, 2014). "To specifically determine if NLRP3 inflammasome activation by ASC/caspase-1 is the primary source of protective IL-1β in the context of Tc infection, we conducted further studies in primary bone marrow-derived mφs from NLRP3-/- mice and matched controls." (PMID 25372293, 2014). "Inflammasome-mediated activation of caspase-1 also triggers programmed lytic cell death termed pyroptosis, a process frequently induced by infection and results in cell burst releasing cytosolic contents such as cytokines or recalcitrant pathogens." (PMID 25306446, 2014). "In agreement with previously published data, infection with Fn resulted in cleavage of caspase-1 as noted by the appearance of caspase-1 p10 subunit." (PMID 25191316, 2014). "Cleavage of procaspase-1 to caspase-1 requires TLR2, as TLR2−/− mouse macrophages showed little caspase-1 24 h after infection with LVS." (PMID 24600590, 2014).
infection (continued). "Previous work has suggested that infection with B. pertussis leads to activation of the NLRP3/caspase-1 inflammasome and this activation depends on the pore-forming activity of the adenylate cyclase toxin." (PMID 25198773, 2014). "Consistently, the FLICA assay, which employs the fluorescent probe FAM-YVAD-FMK and Western blot, indicate that infection with P. chabaudi is sufficient to promote caspase-1 activation." (PMID 24453977, 2014). "Yet in vivo with a live infection, IL-1β levels in the lung are unaffected by loss of ASC or caspase-1 and bacterial burden and mortality in inflammasome-deficient mice are not significantly different from WT mice." (PMID 24409181, 2013). "A/J mice express a hypomorphic allele of NAIP5, and A/J macrophages still activate caspase-1 in response to WT Lp under certain infection conditions." (PMID 24409420, 2013). "Another recent report revealed that activation of Rac1 in response to infection is important to NLRP3/ASC-dependent caspase-1 activation in response to Chlamydia pneumoniae by human mononuclear cells." (PMID 24324933, 2013). "Another possible mechanism of T3SS needle tip complex-induced cellular damage/death during the late phase of infection is engagement of inflammasomes and activation of caspase-1." (PMID 24312357, 2013). "To clarify how h1 deletion affects caspase-1 activation upon infection by V. parahaemolyticus, we examined the amounts of released IL-1β and IL-18 from the infected BMMs with or without LPS pretreatment." (PMID 23357873, 2013). "The NLR family member proteins NLRP3 and NLRC4 are known to recognize infection with various pathogens and to mediate caspase-1 activation by forming a complex with adaptor protein ASC." (PMID 23357873, 2013). "Inhibition of caspase-1 activation by YopM impaired induction of pyroptosis, demonstrating that the effector modulates inflammatory cell death during infection." (PMID 24324933, 2013). "In this study, we found that murine bone marrow-derived dendritic cells responded to P. brasiliensis yeast cells infection by releasing IL-1β in a spleen tyrosine kinase (Syk), caspase-1 and NOD-like receptor (NLR) family member NLRP3 dependent manner." (PMID 24340123, 2013). "Casp1−/− mice had more severe inflammation and injury in the cecum and higher bacterial burden in all organs indicative of caspase-1 role in protecting mucosal surfaces and containing infection." (PMID 23977202, 2013). "In summary, the infection of murine dendritic cells with the primary fungal pathogen P. brasiliensis primes, via Syk signaling, and activates the caspase-1-dependent NLRP3 inflammasome." (PMID 24340123, 2013). "Caspase-1 activation and IL-1β processing were markedly attenuated after infection with the TdhA mutant (ΔtdhA)." (PMID 23357873, 2013). "Caspase-1-, ASC-, and IL-18-deficient mice are all more susceptible to infection with the intracellular bacterium Anaplasma phagocytophilum as a result of inadequate Th1 activity." (PMID 24409181, 2013). "The importance of IPAF-dependent activation of caspase-1 has been highlighted in infection models in vitro using Salmonella typhimurium, S. flexneri, Legionella pneumophila, and P. aeruginosa." (PMID 24273538, 2013). "We compiled all of the CFU data from experiments that we performed using WT, TLR5−/− and Casp1−/− mice in infections with WT, flagellin-null and flgM− Salmonella." (PMID 23977202, 2013). "To further investigate the mechanisms responsible for caspase-1 activation by V. parahaemolyticus, we next examined caspase-1 activation in NLRP3- or NLRC4-deficient macrophages in response to infection with V. parahaemolyticus." (PMID 23357873, 2013). "Inflammasomes are multimeric protein complexes that respond to infection by recruitment and activation of the Caspase-1 (CASP1) protease." (PMID 23818853, 2013). "Caspase-1 activation and the processing/release of IL-1β upon infection with ΔtdhAS were partially but significantly enhanced by the knockdown of ATG5." (PMID 23357873, 2013).
infection (continued). "Of note, flagellin recognition via Naip5/Nlrc4/caspase-1 account to infection control in vitro and in vivo." (PMID 24324933, 2013). "Studies in knockout mice have demonstrated that caspase-1 is important for primary clearance of L. monocytogenes, but the role of other caspases in the innate immune response to infection is less well defined." (PMID 22807671, 2012). "Most interesting is the implied difference in regulatory T lymphocyte populations, evident from FOXP3 promoter site enrichment, and the potentially enhanced IL-1β expression as a result of greater up-regulation of CASP1 in the CA04 infection." (PMID 22937776, 2012). "The conditions used for infection of macrophages with Yersinia affect the outcome of YopJ-mediated caspase-1 activation." (PMID 22563435, 2012). "The results of molecular chaperone mRNA levels in baculovirus-infected normal and Sf-caspase-1-repressed stable cells demonstrated that these cells were appeared in different states during the infection progression." (PMID 23134743, 2012). "In the low MOI infection conditions used here, it is likely that low amounts of YopJ are injected into macrophages, resulting in a delay in cell death and caspase-1 activation in macrophages." (PMID 22563435, 2012). "This is in line with recent studies showing that infection of cells with C. trachomatis and C. pneumoniae led to activation of caspase-1 depending on NLRP3 and ASC inflammasome." (PMID 22276187, 2012). "Culture supernatants from LPS-primed wild-type BMDMs contained the caspase-1 p10 subunit after infection with OT." (PMID 22723924, 2012). "Even after 5 days of infection, we observed more than 1.5-folds increase in caspase-1 activity over that of mock-infected mice brain and the levels gradually decreased thereafter." (PMID 22393394, 2012). "Caspase-1, known as an inflammatory caspase, plays a key role in the innate immune response of macrophages to various infections." (PMID 22558425, 2012). "NLRP3 inflammasome serve as the platform for caspase-1 activation (and IL-1β release) during infection with both DNA (adenovirus, herpes virus, vaccinia virus) and RNA (influenza A virus, mouse Sendai virus, mouse encephalomyocarditis virus) viruses." (PMID 22295065, 2012). "IL-1β release during infection requires NLRP3/ASC inflammasome complex that activates caspase-1, the enzyme required for processing pro-IL-1β into mature IL-1β." (PMID 22295065, 2012). "IL-1β is generated from cytoplasmic pro-IL-1β, which is cleaved by caspase-1 in response to infection, inflammation or immunological challenges." (PMID 21249123, 2011). "A consequence of caspase-1 activation in macrophages following infection by NLRC4-activating pathogenic bacteria (see Section 3.1) is a rapid, and caspase-1-dependent cell death called pyroptosis." (PMID 22019906, 2011). "Since CP is an obligate intracellular pathogen, we analyzed lung cells by intracellular flow cytometry after infection by CP in Casp1−/− mice vs. WT mice." (PMID 21731762, 2011). "Pyroptosis of macrophages following infection with S. typhimurium occurs after the caspase-1-dependent formation of pores (1.1–2.4 nm in diameter) in the plasma membrane." (PMID 22019906, 2011). "Examination of the bronchoalveolar lavage fluid (BALF) and lung homogenates from CP infected Casp1−/− mice revealed significantly greater leukocyte recruitment, particularly of macrophages and lymphocytes, at days 12 post infection compared to WT mice." (PMID 21731762, 2011). "These resultsdemonstrate that apoptosis can occur in Yp-YopJKIM -infectedmacrophages in the absence of NLRP3, NLRC4 or ASC, consistent with our previousdata showing that macrophage apoptosis during Yp-YopJKIM infection isindependent of caspase-1." (PMID 21533069, 2011). "Infection of macrophages with Listeria monocytogenes induces the activation of caspase-1 via NLRP3, NLRC4 and AIM2 inflammasomes." (PMID 22019906, 2011).
infection (continued). "Taken together, these results indicate that Casp1 plays a key role in initiation of early inflammatory responses that lead to bacterial clearance in the lungs and survival from infection." (PMID 21731762, 2011). "More recently, it has been demonstrated that the AIM-2 inflammasome mediates caspase-1 activation and secretion of mature IL-1β and IL-18 during FT infection." (PMID 21819572, 2011). "A high MOI followed by 1 hrof bacterial-host cell contact before addition of gentamicin results in detectableYopJ-dependent apoptosis and caspase-1 activation within 2 hr of infection but nodetectable secretion of IL-1β by this time point (data not shown)." (PMID 21533069, 2011). "At this infectious dose, Casp1−/− mice exhibit significantly greater mortality, pulmonary bacterial titers and inflammatory lung damage (12 days post-infection) compared to wild-type C57BL/6 (WT) mice." (PMID 21731762, 2011). "Since caspase-1-activation during infection of HeLa cells has recently been demonstrated in Chlamydia infected cells, it was also a possibility that part of the effect of WEHD-fmk was due to caspase-1 inhibition." (PMID 21990969, 2011). "Activation of caspase-1 was measured by immunoblotting to detect the cleavedenzyme in lysates prepared 2 hr after infection ofIkkβΔ orIkkβF/F BMDMs with Yp-YopJKIM,Yp-YopJCO92 or Yp-YopJC172A." (PMID 21533069, 2011). "MatureIL-1β was absent in supernatants isolated fromcasp-1-/- BMDMs infected withYp-YopJKIM, indicating that the processing andrelease of IL-1β during infection of wild-type macrophages withYp-YopJKIM occurred in a caspase-1-dependent manner." (PMID 21533069, 2011). "Early rIL-1β treatment during infection (i.e. days 0, 1, and 2 post-infection) rescued Casp1−/− mice, restored survival and reduced lung bacterial load." (PMID 21731762, 2011). "We observed increased levels of active caspase-1 in the livers of wild-type mice compared to TLR2−/− mice 4 h post-infection." (PMID 21698237, 2011). "Under the low MOI conditions the presence of 30 mM KCl in the infection mediuminhibited the secretion of IL-1β and IL-18 from macrophages infected withYp-YopJKIM, suggesting an important role for K+efflux in caspase-1 activation." (PMID 21533069, 2011). "Resistance to infection required the actions of both caspase-1 and IL-1β as Nlrp1bS/S mice deleted of caspase-1 or the IL-1 receptor, or treated with the Il-1 receptor antagonist anakinra, were sensitized to infection." (PMID 21170303, 2010). "Kinetic analysis in B6 macrophages infected with wild type M. marinum showed that caspase-1 p10 appeared 8 hrs post infection, suggesting that the bacteria interacted with the host cytoplasm at this time to activate an inflammasome." (PMID 20463815, 2010). "A similar result was obtained in a caspase-1 knockout mouse in the C3H/HeN (Nlrp1bS/S) background, when infection was by the intraperitoneal (IP) route." (PMID 21170303, 2010). "Previous studies concluded that infection with Legionella activates Naip5 by delivering flagellin through its type IV secretion system, which then induces Ipaf-mediated caspase-1 activation and cell death to restrict Legionella replication." (PMID 20671924, 2010). "IL-1β cleavage is a hallmark of inflammasome activation, and we observed significant Pycard, Nlrp3, and Casp-1-dependent inflammasome activation during in vitro infection of cultured cells." (PMID 20808838, 2010). "A single i.v. injection of invasive M90TΔaroA resulted in caspase-1 dependent apoptosis of TAMs followed by a 74% reduction in tumors of transgenic MMTV-HER-2 mice 7 days post infection." (PMID 20221397, 2010). "After infection with invasive M90TδaroA shigellae, caspase-1 activation was detectable in total cells and macrophage fractions of tumors taken 6 hours after infection." (PMID 20221397, 2010). "Flagellin-independent caspase-1 activation by S. Typhimurium was reported to require increased multiplicities of infection." (PMID 20814576, 2010).